INS (insulin)
Diseases named in the same sentence as INS in open-access papers (continued):
Sharing a sentence is not in itself a finding about the gene and the disease.
diabetes (continued). "Insulin treatment may restore the increase of Aβ level induced by diabetes." (PMID 25540622, 2014). "In the UK Prospective Diabetes Study (UKPDS) completed in 1998, overall microvascular complications were reported to be less prevalent in patients receiving intensive antidiabetic therapies based on sulfonylurea-insulin, a risk which was sustained through the 10 year follow-up period." (PMID 25410473, 2014). "Insulin-treated patients usually show a longer duration of diabetes and a higher prevalence of diabetes complications and it is possible that some studies, which did not provide adjustments for such confounders, could have overestimated the negative impact of insulin treatment." (PMID 25140176, 2014). "This meta-analysis suggested that insulin prescription of DM may not have much impact on the relationship between diabetes and risk of PD, whereas oral anti-diabetes drug appeared to increase PD risk." (PMID 24465703, 2014). "Diabetes mellitus (DM) is characterized by chronic hyperglycaemia which is resulted by the defects of insulin secretion or action." (PMID 24738047, 2014). "Future studies on the interplays among HMGA1, PDX-1, and MafA might be useful in understanding the molecular basis of clinical phenotypes in certain clinical conditions where insulin secretion becomes compromised (i.e., diabetes mellitus and other categories of glucose intolerance)." (PMID 25628604, 2014). "Of note, two of those patients suffered from diabetes (40% of all diabetic patients in this cohort), a sub-cohort maybe especially prone to post-therapeutic hyperkalemia due to reduced sensitivity to endogenous insulin." (PMID 25977880, 2014). "Diabetes mellitus (DM) is a set of metabolic disorders characterized by hyperglycemia resulting from defects in insulin secretion and/or action." (PMID 25280384, 2014). "Fasting insulin in normoglycemic adults is an important predictor of diabetes risk independent of whether they have insulin resistance or not." (PMID 25960772, 2014). "Diabetes Mellitus (DM) is a chronic disease characterized by hyperglycemia, as a result of abnormal insulin production, insulin function, or both." (PMID 25332855, 2014). "Even though the currently available drugs (insulin, sulfonylureas, biguanides, and thiazolidinediones) may be valuable in the management of diabetes, these drugs are usually accompanied by considerable side effects such as hypoglycemia, drug resistance, edema, and weight gain." (PMID 25593725, 2014). "Actually, MIF might be involved in diabetes pathogenesis in much more ways: regulation the insulin secretion, modulation inflammation such as exacerbates insulitis and local pancreatic inflammation, contribute to beta cell apoptosis in cooperate with other toxics." (PMID 24708788, 2014). "Indeed, the regulatory molecules controlling insulin granule synthesis and secretion are not fully understood and may be exploited therapeutically to prevent or delay the progression of diabetes." (PMID 25144761, 2014). "Diabetes mellitus (DM), especially type-1 DM, has been associated with variations of different exhaled biomarkers, but a study has shown that one of these potential biomarkers, acetone, could not discriminate between 20 healthy controls and 15 CF patients of whom 6 received insulin due to CFRD." (PMID 25542036, 2014). "Indeed, in contrast to liver, muscle and adipose tissue where diabetes-induced increase in plasma insulin is compensated by diabetic insulin resistance, insulin-sensitive cancer cells in the diabetes context are exposed to high insulin and IGF-1 acting as growth factors." (PMID 25375205, 2014). "Participants without diabetes but at the higher levels of fasting glucose, fasting insulin, HbA1c and HOMA-IR spectrum may also be at greater risk of glaucoma." (PMID 25393836, 2014).
diabetes (continued). "In relation to this, our study participants, who have a median age of 60 and are in the early stages of diabetes progression, may represent a more insulin resistant phenotype in which the functional β-cell machinery is still able to compensate for diminishing insulin sensitivity." (PMID 25157406, 2014). "Diabetes mellitus (DM) is related to a group of metabolic diseases characterized by a chronic hyperglycemia attributed to an inadequate secretion or diminished action of insulin." (PMID 25713640, 2014). "Better diabetes management with earlier initiation and optimisation of insulin regimens (e.g., with insulin analogues in the A1chieve population) may reduce the prevalence of vascular complications, improve the lives of people with diabetes and reduce the burden on healthcare systems." (PMID 24228724, 2013). "Since skeletal muscle represents a major site of insulin-dependent glucose uptake and utilization, arginase-mediated endothelial dysfunction may limit skeletal muscle perfusion and exacerbate hyperglycemia in diabetes." (PMID 23730303, 2013). "Second, we did not have data on several aspects of diabetes that may potentially influence risk of colorectal cancer, including diabetes duration, anti-diabetic medications including insulin." (PMID 24069323, 2013). "The purpose of this study was to collect data on the capacity and effectiveness of etanercept to prolong endogenous insulin production and was founded on hypothesis that the administration of etanercept could extend the period of partial remission of diabetes (“honeymoon”)." (PMID 24124913, 2013). "Although these results are in agreement with observations that administration of melatonin and pinealectomy affect metabolic disturbances related to plasma insulin and diabetes, doubts remain as to whether the described effects after STZ application can be generalized." (PMID 23535335, 2013). "In early stage of type 2 diabetes mellitus, peripheral tissues such as liver, muscle, and adipose tissues are not sensitive towards insulin and they cause common symptoms such as increased thirsty, frequent urinary, ketonuria and ketonemia in diabetic patients." (PMID 23762147, 2013). "In addition, we examined whether hyperglycemic correction with insulin would restore sevoflurane post-conditioning in diabetes." (PMID 23991188, 2013). "Moreover, the vaccine investigated in this study could be supplemented in the future with an additional viral construct expressing proinsulin (rVV-CTB::INS), which we demonstrated earlier to provide dramatic suppression of new diabetes onset in NOD mice." (PMID 24319466, 2013). "In our study, induction of type 2 diabetes showed significant increased blood glucose level and decreased body weight and insulin level compared to control rats which confirm the induction of diabetes, and it may be due to partial necrosis of pancreatic β-cell by STZ." (PMID 23936668, 2013). "Therefore, these mutual effects clearly showed that ETH and DTH extracts and corymbiferin are beneficial for attenuating diabetes mellitus through inducing IRS serine/threonine phosphorylationthe, since overproduction of ROS can impair insulin signaling caused by oxidative stress in diabetic rats." (PMID 24250711, 2013). "Since EA has been shown to improve insulin activity in our previous studies, a combination of EA's effects in terms of enhancing insulin activity with the use of an insulin sensitizer may potentially be a new modality for the treatment of diabetes mellitus in humans." (PMID 23983807, 2013). "Steady-state response curve between pAKT (output) and insulin (input) was calculated for different model parameter values which led to the partitioning of the parameter space into regions for the normal response and disease phenotypes including cancer and diabetes." (PMID 24400038, 2013).
diabetes (continued). "In addition to impaired pancreatic insulin secretion and peripheral insulin action, pathological α-cell physiology and glucagon release also play important roles in initiating and maintaining hyperglycemic states in diabetes." (PMID 23535335, 2013). "This apparent difference may be because first phase insulin secretion is normal in the IUGR lamb at this age, whereas previous reports of increased first phase insulin responses after exendin-4 or GLP-1 treatment have all been in the context of diabetes, when first phase secretion is impaired." (PMID 23424667, 2013). "Significance: The new therapeutic candidate may help to reduce insulin need in diabetes." (PMID 23744070, 2013). "Therefore, searching for differentially expressed genes involved in the onset of insulin resistance in insulin-sensitive and insulin-producing tissues from patients with diabetes may help us to understand the molecular mechanisms involved in T2DM." (PMID 23922760, 2013). "However, weight loss is not required for resolution of diabetes, and some drugs increase body weight while improving insulin sensitivity, such as the thiazolidinediones." (PMID 24772374, 2013). "There is ample time for transition between functional depletion of insulin in beta cells and their demise that may allow the salvaging of dedifferentiated beta cells; this presents a novel approach for treating beta cell dysfunction in diabetes." (PMID 23542897, 2013). "Once these pro-inflammatory mediators are activated, they may not only damage the β-cells but can also diminish the potential capacity of remaining β-cells to secrete adequate amount of insulin according to the requirement of blood glucose in both types of diabetes." (PMID 23409091, 2013). "Early disease is characterised by insulin resistance, and epithelial tissues may be exposed to raised insulin levels but with more advanced diabetes the pancreas may fail resulting in low insulin exposure but if systemic insulin therapy is administered then exposure may again be increased." (PMID 23907184, 2013). "Thus, the present data provide new evidence in the cynomolgus monkey model of dysmetabolism and diabetes that in addition to the β-cell insulin hypersecretion, reduction in hepatic insulin clearance possibly due to a saturation mechanism also contributes to the development of hyperinsulinemia." (PMID 23886319, 2013). "However, despite the clear advantages to health associated with good glycaemic control, insulin therapy does not completely eliminate the physical and psychosocial burden of diabetes." (PMID 23199058, 2013). "Some extracts and/or isolated compounds at various doses and in various combinations are beneficial in, among other things, the treatment of latent diabetes mellitus and the complex treatment of insulin-independent DM." (PMID 24304585, 2013). "However, the s with diabetes included in our study were treated with biguanides or sulfonylurea drugs, or insulin, or a combination of oral and insulin therapyies and thus these therapeutic strategies could have an effect on the serum adiponectin levels." (PMID 23819115, 2013). "Altogether, our data suggest that in addition to insulin secretion in the islets of Langerhans and the brain-centered glucoregulatory system, amino acid metabolism and amino acid transporters might also be potential therapeutic targets in diabetes." (PMID 24427154, 2013). "Also the metabolic control of diabetes improved and the HbA1c after three months from the starting of biological therapy was 8.7% (71 mmol/mol) and after 6 months was 8.3% (67 mmol/mol) while the insulin dose decreased respectively to 1.0 and 0.8 units/Kg/day." (PMID 24124913, 2013). "Capable of secreting insulin to reduce hyperglycemia after transplantation in diabetic animals, the resulting islets might become a potential source for islets transplantation in treatment for diabetes." (PMID 24268157, 2013).
diabetes (continued). "Diabetes mellitus (DM) is a chronic metabolic disorder characterized by high levels of glucose in the blood due to the impaired secretion of insulin or insulin insensitivity." (PMID 23414307, 2013). "Of the remaining pathways, Neurotrophin signaling pathway, Insulin signaling pathway, and Type II diabetes mellitus are enriched by target-related proteins of vitexicarpin, suggesting that it may be potentially used for the diabetes therapy." (PMID 23476684, 2013). "The relevance of these findings may be in that inhaled formulations of insulin that were once promising, approved strategies for treatment of diabetes mellitus in US and Europe have been withdrawn due to persistent reports of respiratory problems, including cough." (PMID 24204385, 2013). "Whether the disparity identified in our study in SMBG frequency for women not on insulin therapy translates to poor diabetes self-management, or to increased health risk to women with diabetes, remains to be seen and warrants further research." (PMID 24262007, 2013). "Therefore, exogenously administered insulin in diabetic patients might compensate diabetes induced sKlotho depletion by increasing sKlotho shedding from the cell membrane." (PMID 23945089, 2013). "Prior to this visit, she managed her diabetes with insulin glargine 75 units subcutaneously in the morning and 25 units at night, metformin ER 2000 mg once daily, and insulin aspart at mealtime using a coverage scale, as the patient and parents were reluctant to use scheduled mealtime insulin doses." (PMID 24222881, 2013). "There should be a stepwise increase in insulin and C-peptide release as a function of increasing glucose concentrations in vitro, cure of hyperglycaemia following cell transplantation in diabetic animals, and prompt return of diabetes when these cells are removed." (PMID 23762531, 2013). "Additionally diabetes technologies such as continuous subcutaneous insulin infusions(CSII,insulin pumps) were mostly concentrated in minority of clinics, meaning that young adults from outside these clinics’ catchment areas had fewer opportunities to obtain these devices." (PMID 24168159, 2013). "Our data suggest that sitagliptin accelerates normalization of blood glucose level in a diabetes model by stabilizing Glp-1, which in turn results in increased insulin production which may be due to an increase in β-cell mass, VEGF expression and vascularization." (PMID 24349326, 2013). "Subsequent phenotype and genotype relationship analysis indicated rs4074134 or other variations in linkage equilibrium might affect insulin sensitivity rather than beta cell function, which in turn may alter the risk for pre-diabetes and T2DM." (PMID 23431394, 2013). "Therefore, the present study tends to investigate the effect of streptozotocin-induced diabetes before pregnancy and preexisting maternal diabetes on serum glucose, insulin concentration, insulin resistance, insulin sensitivity, and β-cell function of offspring at different postnatal periods." (PMID 23998129, 2013). "Furthermore, insulin may be the first agent prescribed to newly diagnosed individuals with severely uncontrolled diabetes." (PMID 24223860, 2013). "Diabetes mellitus: Any of the following situations: 1) A casual preoperative glicemia the same or greater to 200 mg/dl (11.1 mmol/l), glicemia in preoperative fasting same or grater to 126 mg/dl (7 mmol/l), 2) Regular ingestion of oral hypoglycemiants or regular application of insulin." (PMID 23829692, 2013). "We explored the agreement between self-report of diabetes, identification of diabetes diagnostic codes in APDC data, claims for glycosylated haemoglobin (HbA1c) in MBS data, and claims for dispensed medication (oral hyperglycaemic agents and insulin) in PBS data." (PMID 24245780, 2013). "This may also benefit the patients with type 2 diabetes mellitus (T2DM) who need exogenous insulin." (PMID 22935022, 2013).
diabetes (continued). "Diabetes mellitus (DM) is characterized by hyperglycemia resulting from defects in insulin secretion, insulin action, or both." (PMID 23577036, 2013). "Also, if the eastward travel formula shows a requirement for only a small insulin dose to cover just a few hours of time before the next scheduled full dose of basal insulin, many diabetes care providers would recommend skipping that dose, again to mitigate the risk of hypoglycemia." (PMID 24360506, 2013). "Our results suggest that aminoguanidine is not hepatotoxic, when used at dosage of 1 g/L for the treatment of diabetes complications, and confirmed that the practice of moderate physical exercise assuaged the damage caused by diabetes without the use of insulin." (PMID 23837632, 2013). "Although this is a good operational definition, according to glycemic and pharmacological criteria, it does not account the underlying beta-cell function and insulin action and thus may be inappropriate to define a cure of diabetes." (PMID 23840207, 2013). "Diabetes was associated with an increased risk of falling for patients not treated with insulin." (PMID 23785355, 2013). "While acknowledging that cost-containment pressures in Irish diabetes health services were impacting on the care they could provide, consultant’s also noted positive aspects in that the health services still provided diabetic patients with free insulin, glucometers and diabetes-related medication." (PMID 24168159, 2013). "This increase may be due to the effects of external insulin injection during diabetes duration." (PMID 24298385, 2013). "Although the mechanisms underlying the development of cognitive dysfunction in diabetes have not been completely elucidated, hypotheses such as oxidative stress and insulin/insulin receptor-mediated signal transduction are gaining more attention." (PMID 24386004, 2013). "She had a history of type 1 diabetes mellitus (DM) and has been on insulin therapy for the past 13 years." (PMID 24392215, 2013). "Thus, early education at the point of diagnosis regarding the progressive nature of diabetes and inevitable use of insulin could allay their misconceptions." (PMID 24164794, 2013). "In the field of diabetes, some games for education of patients, and a few technology-based initiatives for education of health professionals have been described, but to our knowledge, no game have been reported for education of health professionals on diabetes or insulin." (PMID 23612462, 2013). "Further work is needed to clearly determine how they regulate the insulin signaling in hepatocytes and influence insulin sensitivity in other tissues (e.g., muscle and adipose tissue) in rodents and human and their contribution to glucose homeostasis in diabetes." (PMID 23762871, 2013). "Furthermore, previous research has shown that diabetes-specific quality of life as measured by the ADDQoL distinguishes between insulin treated and non-insulin treated patients, and is sensitive to the presence of diabetes complications but is unaffected by comorbidity unrelated to diabetes." (PMID 24131673, 2013). "J-15 presented with extremely low pre-treatment insulin levels (14 μU/mL), significant hyperglycemia (275 mg/dL, fed glucose) and low body weight (<10 kg at study intake) representative of a more advanced stage of diabetes disease as compared to 5 other monkeys in the main cohort." (PMID 23823755, 2013). "Furthermore, the honeymoon period, a period after the initial treatment of diabetes, in which the insulin production temporarily regenerates, reduces average insulin requirement in the previously analyzed group of pediatric patients with type 1 diabetes <20 years of age." (PMID 23967077, 2013). "Interestingly, when focusing on the answers of the patients concerning our question of the most annoying thing in their daily diabetes care, we found that our patients are just as annoyed by insulin injection as to having self-protocol the therapy in a booklet or electronic device." (PMID 24344648, 2013).